CCL2 (C-C motif chemokine ligand 2)
Diseases named in the same sentence as CCL2 in open-access papers (continued):
Sharing a sentence is not in itself a finding about the gene and the disease.
Stroke (continued). "In the ischemic penumbra of stroke models, Chemokine ligand 2 (CCL2) levels increase as early as 6 h of reperfusion with peak levels with induction of leukocyte recruitment and disruption of BBB integrity." (PMID 34596819, 2022). "Meanwhile, deficienc in CCL2 and CCR2 greatly reduce the recruitment of macrophages after stroke, the size of the cerebral infarction area, and the degree of BBB disruption after ischemia-reperfusion injury." (PMID 34276530, 2021). "This indicates that infiltration of peripheral immune cells through the CCL2/CCR2 axis contributes to the neuroinflammation present after experimentally induced stroke." (PMID 33918875, 2021). "Neutrophils and monocytes infiltrate the brain parenchyma after stroke onset, with monocytes being recruited preferentially through the chemokine (C-C motif) ligand 2/C-C chemokine receptor type 2 (CCL2/CCR2) axis." (PMID 33918875, 2021). "Overexpression of CCL2 has been shown to increase macrophage infiltration and the area of cerebral infarction at the injury site, suggesting that CCL2 can induce post-stroke inflammation and adversely affect post-stroke recovery." (PMID 34276530, 2021). "This migration of inflammatory cells is promoted by CCL2/CCR2 interactions, which induces translocation of CCR2-expressing inflammatory cells into infarct areas already experiencing increased CCL2 expression following a stroke." (PMID 33096826, 2020). "CCL2 is a pro-inflammatory chemokine that plays an important role in inflammatory reactions under various neurological conditions, such as stroke, Alzheimer’s disease, and multiple sclerosis." (PMID 33096826, 2020). "It involves the stroke-mediated decrease of miR-98 and let-7g*, which in turn, triggers expression of pro-inflammatory mediators, such as CCL2, CCL5, CXCL1, and IP-10." (PMID 32766248, 2020). "In the present study, we found sustained elevations of CCL2 levels in the brain at 28 days after stroke induction in the CCL2-MSC group as compared with levels in the other groups." (PMID 33096826, 2020). "Previously studies suggest that increased CCL2 levels in stroke exacerbate neuro-inflammation and subsequent brain injury, thereby increasing stroke volume and resulting in poor prognosis." (PMID 33096826, 2020). "Previous studies have shown that the expression of Ccl2 is highly increased in the brain after stroke, and that silencing the Ccl2 gene is protective in stroke models." (PMID 33297959, 2020). "Stroke caused an increased release of cytokines/chemokines such as CCL and its ligands MCP-1/CCL2, IP-10/CXCL10, and RANTES/CCL5." (PMID 33177990, 2020). "CCL2 is constitutively present in the normal brain and within neurons, astrocytes, and endothelial cells; however, it is upregulated during a stroke." (PMID 33096826, 2020). "Peripheral blood monocytes/macrophages have also been shown to migrate to and infiltrate into ischaemic brain tissue under the action of C-C chemokine ligand 2 (CCL-2) and to promote inflammation and tissue damage in the brain after stroke." (PMID 30700305, 2019). "In summary, the major effects of MLC901 are the reduction of neutrophil recruitment, the reduction of microglia activation and the reduction of pro-inflammatory mediators (TNFα, IL6, IL1β, CCL2) production induced by stroke." (PMID 30584250, 2018). "One potential candidate molecule for recruiting MDMs from CSF towards the ischemic lesion is the chemokine CCL2, which was found to be increased in the ischemic cortex of mice and in the CSF of stroke patients." (PMID 28754163, 2017). "Expression of CCL2 was significantly greater in the plasma, epididymal fat and liver of obese mice prior to stroke compared with control mice." (PMID 28798136, 2017). "Choroid plexus tissues were collected and analyzed for Vcam1, Madcam1, Cx3cl1, Ccl2, Nt5e, and Ifnγ expression at different timepoints after stroke using qPCR." (PMID 28754163, 2017).
Stroke (continued). "An exception to the pattern of increased peripheral inflammation in ob/ob mice after stroke was the reduction in levels of CCL2 (MCP-1)." (PMID 28798136, 2017). "When comparing SHR and WKY subjected to stroke, we observed a significantly higher expression of CCL2, CCL7, and CXCL2 in SHR." (PMID 26640428, 2015). "The increase in brain chemokine expression observed here is in contrast to that in mice fed a high-fat ‘diabetic’ diet where a blunted chemokine (CCL2) and cytokine (interleukin-6) response after stroke is observed." (PMID 26239227, 2015). "Previous research with regard to stroke has also demonstrated that overexpression of CCL2 can aggravate ischemic brain injury, and inhibiting the expression of CCL2 can reduce injury." (PMID 25009636, 2014). "For instance, in a model of stroke CCL2 knockout mice have decreased BBB permeability compared to wild-type mice." (PMID 25012628, 2014). "There is also upregulation of expression of some chemokines like CCL2 in the CSF and serum of patients with stroke." (PMID 24324296, 2013). "Studies in experimental stroke (middle cerebral artery occlusion model (MCAo)) confirmed involvement of chemokine CCL2 and its receptors CCR2 in stroke development." (PMID 24324296, 2013). "Several studies suggest a detrimental role for CCL2 in the progression of stroke injury, as both CCL2-/- and CCR2-/- mice exhibit reduced infarct volumes compared to wild-type controls." (PMID 22340958, 2012). "Transgenic mice over-expressing Ccl2 in the central nervous system (CNS) exhibit a robust accumulation of macrophages in the brain, whereas mice deficient in the Ccl2 gene show reduced leukocyte infiltration after TBI, spinal cord injury and stroke." (PMID 20942978, 2010). "IL-1β and CCL2 have a promoting effect on post-stroke inflammation." (PMID 40948793, 2025). "After the stroke, astrocytes can promote the migration and infiltration of monocytes from circulation, spleen, and bone marrow into the brain parenchyma, mainly through the CCL2/CCR2 axis." (PMID 40289984, 2025). "Conversely, CCL2 may aid stroke recovery by attracting neural progenitor cells to the brain’s damaged regions, whilst CCL5 can safeguard neurons in per-infarct regions through the production of neurotrophic factors." (PMID 38861234, 2025). "In addition, Ccl2, a member of the cytokine–cytokine receptor interaction family, plays a vital role in stroke pathophysiology." (PMID 39507105, 2024). "Moreover, we observed a partial but significant rescue of CCL2 overproduction in Slc4a4-icKO mice after stroke by an overall NOS inhibition." (PMID 38709635, 2024). "In stroke models, it is demonstrated that infiltrating T lymphocytes (e.g., Th17 and Th1 cells) might regulate cytokines (e.g., Infγ and Il-17), chemokines (Ccl2 and Cxcl1), or ROS to degrade tight junction in the BBB." (PMID 37443034, 2023). "Moreover, Il10-KO CD8+ TRL–treated mice exhibited increased brain expression of IL-6, CCL1, and CCL2 after stroke compared with WT CD8+ TRL–treated mice." (PMID 35912857, 2022). "CCL2/CCR2 also plays an important regulatory role in post-stroke inflammation." (PMID 36742051, 2022). "Other studies also disclosed the functional benefits of the CCR2 over-expression, specifically alleviating post-stroke cognitive impairment by enhancing microglia/macrophage M2 polarization and probably through suppressing the CCL2-induced hematogenous macrophage migration and activation." (PMID 34031863, 2021). "Our results confirmed that both CCR2 and CCL2 levels increased in brain parenchyma during acute phase after stroke, and that CCL2-overexpressing hUC-MSCs more effectively entered the brain parenchyma relative to naïve hUC-MSCs and distributed more densely around areas of upregulated CCR2." (PMID 33096826, 2020). "Both miRs significantly reduced the stroke-induced increase in CCL2 (p < 0.05) and CCL5 (p < 0.01)." (PMID 32766248, 2020).
Stroke (continued). "VISTA could be involved in the microglia response/migration to Ccl2, which would have ramifications particularly during CNS diseases where Ccl2 production is increased such as MS, traumatic brain injury and stroke." (PMID 32856125, 2020). "In conclusion, we demonstrated that CCL2-overexpressing hUC-MSCs effectively restored functional deficits in an animal stroke model by promoting continuous increases in CCL2 levels in the brain, enhancing angiogenesis and neurogenesis, and decreasing neuro-inflammation." (PMID 33096826, 2020). "Therefore, in the present study, we evaluated the potential therapeutic effect and safety of CCL2-overexpressing MSCs in a highly relevant animal stroke model." (PMID 33096826, 2020). "In addition to its well-characterised immune response function, CCL2 has recently demonstrated a pathophysiological role in several CNS diseases such as stroke, epilepsy, ischaemic brain injury, and neurodegenerative diseases." (PMID 32103758, 2020). "Cytometric bead assay revealed a significant increase of interleukin-6 (IL-6) or chemokine ligand 2 (CCL2) protein levels in the ipsilateral cortex of mice suffering from stroke compared with corresponding contralateral cortex or to corresponding sham-operated mice." (PMID 28079884, 2017). "However, stroke then resulted in a significant decrease in CCL2 expression in the plasma and both tissues." (PMID 28798136, 2017). "It was previously demonstrated that CCL2 knockout could depress the decrement of BBB permeability in a rats model of stroke." (PMID 28870240, 2017). "Also, CCL2, which is elevated in neurons by pretreatment with FTY720 and implicated in the development of an ischemia tolerant phenotype in stroke models, is shown to be deleterious when expressed by reactive astrocytes in MS models." (PMID 27617002, 2016). "Indeed, it is believed that the CCR2/CCL2 axis is a potent pathway for «Ly6Chi» inflammatory monocytes recruitment into the CNS in models of stroke, Alzheimer’s disease and EAE." (PMID 27930721, 2016). "Because of the direct upregulation of CCL2 by hypoxia and these signaling intermediary roles, we investigated whether CCL2 participates as a mediator of HPC-induced tolerance to stroke." (PMID 22340958, 2012). "Investigations into inflammatory neuropathologies such as multiple sclerosis and stroke have demonstrated neuroprotection resulting either from interference with the Ccl2 gene, by administration of neutralising anti-CCL2 antibodies, or targeting the CCR2 receptor." (PMID 20942978, 2010). "Besides, Treg cells may protect the integrity of BBB by inhibiting the elevation of matrix metallopeptidase-9 (MMP-9) and C-C motif chemokine ligand 2 (CCL2) in stroke." (PMID 36474712, 2022). "Furthermore, the dysregulation of HGF, TGF-α, and CCL2 in BALF and lung tissue after ischemia could play an important role in the molecular mechanisms underlying stroke-induced lung damage." (PMID 35897671, 2022). "Besides, macrophage influx in response to an increase in CCL2 may enhance post-stroke regeneration via phagocytosis of myelin debris." (PMID 34031863, 2021). "Thus, targeting the inhibition of the CCL2 expression or its receptor CCR2 could improve the prognosis of stroke." (PMID 34276530, 2021). "Furthermore, hypoxic preconditioning induces stroke tolerance in mice via CCL2 signaling pathway." (PMID 33096826, 2020). "Additionally, CCL2 and its receptor CCR2 have been implicated in post-stroke leukocyte trafficking." (PMID 32872405, 2020). "Therefore, we speculated that increased CCR2 levels in the brain following stroke might promote translocation of CCL2-overexpressing hUC-MSCs to the brain parenchyma." (PMID 33096826, 2020). "Also in human stroke patients elevated level of CCL2 was detected in cerebrospinal fluid and serum." (PMID 24324296, 2013).
Stroke (continued). "Commensurate with reduced immune cell recruitment in the brain, we see significantly decreased levels of the chemokines CCL2 and CCL340–42 in Mrgprb2−/− compared to WT stroke hemispheres." (PMID 40712576, 2025). "Further studies using either pharmacological or genetic inhibition of CCL2 and NO demonstrated the role of the Slc4a4 in regulating the CCL2-CCR2 pathway and NO metabolism in the context of BBB recovery after stroke." (PMID 38709635, 2024). "Stroke resulted in upregulated expression of adhesion molecules (P‐selectin, E‐selectin, and ICAM‐1) and chemokines (CC‐chemokine ligand (CCL)‐2, CCL‐3, CCL‐4, CCL‐5, and chemokine C‐X‐C ligand 1 (CXCL‐1))." (PMID 37122157, 2023). "Despite an elevated CCL2 with drug treatment, IRAP inhibition with a low dose of HFI419 reduced stroke related increased forebrain volume suggestive of reduced cerebral oedema." (PMID 37957163, 2023). "This study also found that IGF-1 treatment inhibited levels of inflammatory cytokines such as TNF-α, IL-1β, and IL-6 at 4 h after stroke, while only IL-6 and IL-13 continued to be inhibited at 24 h after stroke, as did chemokines GRO-KC and CCL2." (PMID 37638322, 2023). "In summary, these studies suggest that genetic or pharmacological inhibition of these pro-inflammatory mediators (iNOS, IL-6, CCL2, and CCL9) provides neuroprotection against stroke, which can affect pro-inflammatory mediators by modulating LCN-2." (PMID 35493318, 2022). "Real-time quantitative PCR measurements suggested the prominent elevation of multiple pro-inflammatory cytokines and chemokines, including IL-1β, IL-6, TNF-α, CCL2, CXCL1, and CXCL10 after stroke." (PMID 35761277, 2022). "Of note, the AUCs for GDF-15, D-dimer, ADAMTS13, CCL2/MCP-1, IL-4, CC4b, IL-7, ferritin, SAA, CCL1/I-309 and IL-10 were ≥0.75 in indicating stroke amongst children with TBM." (PMID 33930055, 2021). "In this study, we compared blood TNF, TNFR1, TNFR2, CCL2, and CCR2 levels in stroke patients and healthy controls and investigated the association of TNFR1, TNFR2, CCL2, and CCR2 levels to stroke severity, infarct size, and functional outcome at 90 days." (PMID 33918875, 2021). "Wacker revealed that hypoxic preconditioning induces stroke tolerance via a cascading HIF and CCL2 signaling pathway." (PMID 34707562, 2021). "Our findings showed that the CCL2-MSC group underwent significant functional recovery and displayed decreased stroke volume relative to the M-MSC group." (PMID 33096826, 2020). "LCN2 monoclonal antibody (mAb) specifically targeted LCN2 in vitro and in vivo, attenuating the induction of LCN2 and pro-inflammatory mediators (iNOS, IL-6, CCL2, and CCL9) after stroke." (PMID 32872405, 2020). "At four-weeks post-transplantation, the CCL2-MSC group showed significantly better functional recovery and smaller stroke volume relative to the other groups." (PMID 33096826, 2020). "CCL2 aids in the migration of neural precursor cells and promotes neuroregeneration in patients with TBI and stroke." (PMID 32155215, 2020). "Increases in CCL2 level induce the recruitment of various inflammatory cells to the brain and disruption of the BBB after stroke." (PMID 33096826, 2020). "Taken together, these studies show that genetic or pharmacological inhibition of these pro-inflammatory mediators (iNOS, IL-6, CCL2, CCL9) provides neuroprotection against stroke." (PMID 32872405, 2020). "Western blot analysis confirmed that CCL2 was also significantly increased in post-stroke superficial CLN, accordingly, and MAZ51 treatment reduced CCL2 expression." (PMID 31757960, 2019). "Similar to the effect of miR155, an antagomir for miR210 decreased expression of proinflammatory cytokines IL6, TNFα, IL1β, CCL2, and CCL3 reducing the neurological impairment, putting miR210 as potent regulator of inflammation during stroke recovery." (PMID 31543756, 2019).
Stroke (continued). "This process is exacerbating in stroke, especially in ICH, because CCL2 can exist in more active truncated form under the digestion of plasma plasmin." (PMID 29212271, 2017). "ADFm overexpression in ECs reduced the expression of 11 markers, including CCL2 and ICAM-1, which are known to facilitate macrophage and neutrophil infiltration after stroke." (PMID 26813496, 2016). "At 24 hours post-stroke, IGF-1 treatment continued to inhibit selective pro-inflammatory markers, such as IL-6, the pleitrophic cytokine IL-13 and the chemoattractants CCL2 and GRO-KC." (PMID 24618563, 2014). "Transcripts for the chemokines CCL3, CCL2 and CCL5 were increased in the ischemic hemisphere of wildtype control mice following stroke, with a peak at 12 h for CCL3 and CCL2 and a peak at 7 d for CCL5." (PMID 23301011, 2013). "Regardless, our findings that CCL2 gene deletion, or its immunoneutralization during HPC, robustly blocked HPC-induced stroke tolerance implicates CCL2 in its induction." (PMID 22340958, 2012). "Although different chemokines and receptors, like monocyte chemotactic protein-1 (MCP-1 or CCL2) and CCR2, are involved in immune cell activation and chemotaxis after stroke, an approach aiming at multiple targets remains to be proven." (PMID 21625615, 2011). "Considering the role of CCL2 in chemotaxis and BBB remodeling, our results suggest that pericytes may contribute to immune cell recruitment in the acute phase after stroke." (PMID 37378751, 2024). "We identified Il-1β, Ccl2, Cybb, Wnt9b, as well as some pathway-specific genes such as S100a8 and S100a9 (IL-17 signaling) among the common pro-inflammatory and signaling molecules whose expression was affected by higher TMAO levels in post-stroke animals." (PMID 37175797, 2023). "In addition, CD4+ cells secreting cytokine IL-6, along with mast cells secreting cytokines and chemokines (including IL-1β, TNF-α, CCL2, CXCL10, and GM-CSF) accelerate neurodegeneration, cognitive dysfunction, and stroke." (PMID 35464491, 2022). "Furthermore, a previous study showed the involvement of CCL2 and its receptor “CCR2” in leukocyte trafficking after stroke." (PMID 35493318, 2022). "CCL2/CCR2 interactions contribute to the recruitment of monocytes and neutrophils after stroke." (PMID 36211352, 2022). "Administration of LCN-2 mAb prior to full post-stroke LCN-2 elevation reduced the levels of LCN-2 and pro-inflammatory mediators (iNOS, IL-6, CCL2, and CCL9) and resulted in neutrophil infiltration, BBB leakage, cerebral infarction induction, and improved functional outcomes after stroke." (PMID 35493318, 2022). "In line with Trizol whole-brain mRNA data, Cxcl1 and Cxcl2 levels were profoundly ﻿reduced in Il1−/− mice 24 h after stroke, whereas Ccl2 was not significantly downregulated in input material from Il1−/− mice." (PMID 35384588, 2022). "dBET1 markedly reduced inflammation and oxidative stress after stroke, indicated by multiple pro-inflammatory cytokines and chemokines including IL-1β, IL-6, TNF-α, CCL2, CXCL1 and CXCL10, and oxidative damage markers 4-hydroxynonenal (4-HNE) and gp91phox and antioxidative proteins SOD2 and GPx1." (PMID 35761277, 2022). "However, after stroke or ex vivo stimulation, these cells dramatically increased their production of TNF, IFN-γ, and MCP-1/CCL2." (PMID 34711943, 2022). "Therefore, activation of the CCL2/CCR2 pathway can recruit inflammatory cells and release pro-inflammatory factors, which are detrimental to the stroke prognosis." (PMID 34276530, 2021). "Treatments with LCN2 mAb within a clinically relevant time window significantly attenuated the induction of LCN2 mRNA and protein, pro-inflammatory mediators (iNOS, IL-6, CCL2, CCL9), infiltration of neutrophils, BBB leakage, and cerebral infarction, and improved functional outcomes after stroke." (PMID 32872405, 2020).